GNA11 (G protein subunit alpha 11)
Diseases named in the same sentence as GNA11 in open-access papers (continued):
Sharing a sentence is not in itself a finding about the gene and the disease.
tumor (96 papers, 2009 to 2026). "To achieve sensitive detection of GNAQ/GNA11 mutations, which serve as evidence of the presence of tumor DNA, we conducted deep amplicon NGS on all ocular fluid samples from the 88 UM patients." (PMID 40461505, 2025). "Most studies have utilized deep amplicon sequencing or digital droplet PCR to detect circulating tumor DNA (ctDNA) in UM based on detection of GNAQ/GNA11 gene mutations." (PMID 40461505, 2025). "It is important to note that the CHEK2 variant data of MUM were analyzed from tumor tissue sections, and pathogenic somatic mutations in GNA11 or GNAQ, along with BAP1, were detected alongside the CHEK2 variants in the UM metastatic tissues." (PMID 40283643, 2025). "All seven tumours contained a hotspot variant in either GNAQ (two tumours) or GNA11 (five tumours), consistent with somatic variants in these genes being common initiating events in UMs." (PMID 39766052, 2024). "The variant allele fraction (VAF) of these GNAQ and GNA11 variants indicated their presence in the majority (66–100%) of cells in both Regions A and B of all tumours." (PMID 39766052, 2024). "The research evinced that these mutations were mutually exclusive, except for one tumor that carried them both—at Q209 and R138 in GNA11." (PMID 39518110, 2024). "These factors encompass chromosomal abnormalities, gene mutations (such as GNAQ and GNA11), gene expression profiles, tumor size, tumor location, and histopathological features." (PMID 38724687, 2024). "Somatic genetic analysis on an FFPE sample from the first tumor identified the recurrent p.(Gln209Leu) mutation in the GNA11 gene." (PMID 38892746, 2024). "One patient (25%) exhibited a partial response (this tumor harbored a GNA11 R183C and a BAP1 R385* mutation)." (PMID 38903495, 2024). "We further investigated the association between GNA11 and tumor stage, and found that the expression level of GNA11 in early and advanced stages was significantly lower than that in normal tissue." (PMID 37396036, 2023). "The initiating mutation in GNA11 also determines a more aggressive development of the tumor as compared to GNAQ mutations." (PMID 37958591, 2023). "Among the recurrently mutated genes, GNAQ and GNA11 are involved in the process of carcinogenesis and are mutated in 80–90% of these tumours." (PMID 35804836, 2022). "Contrary to other studies, the GNA11-mutated tumours demonstrated a longer average time to first metastasis (GNA11 vs. GNAQ: 77.8 vs. 43.1 months) and a better OS (79.8 vs. 33.7 months)." (PMID 35804836, 2022). "Previous analyses of cell‐free DNA from plasma had shown detectable levels of tumor‐specific GNAQ/GNA11 mutations in patients with the clinical diagnosis of progressive disease." (PMID 34291585, 2021). "In this mutation sequence, the BAP1 mutation has been assumed to occur relatively late in tumor progression, preceded by oncogenic mutations in G-protein subunits including GNA11 and GNAQ that are present in as high as 83–96% of UM7." (PMID 33903674, 2021). "All four had a GNA11 Q209L mutation, a below median tumor burden and an LDH level below the upper limit of normal." (PMID 33917514, 2021). "Whereas most tumours harbour a hotspot mutation in GNAQ or GNA11, the CYSLTR2 p.L129Q mutation forms a rare alternative." (PMID 33588787, 2021). "The clinical information of 75 ESCC patients including American Joint Committee on Cancer (AJCC) clinical stage and pathological grade was analyzed to explore the association between GNA11 expression and tumor stage." (PMID 34568004, 2021). "Tumor‐specific GNAQ/GNA11 mutations in the cell‐free DNA were determined using deep amplicon sequencing and the proportion of mutant versus wild‐type sequences was used as a measure for the proportion of tumor‐derived DNA in the plasma of the patients." (PMID 34291585, 2021). "The cell‐free DNA was isolated from all samples and analyzed for the presence of the GNAQ/GNA11 mutation, previously found in the matched primary tumor, by deep amplicon sequencing." (PMID 34291585, 2021).
tumor (continued). "Whereas most tumours harbour a mutation in GNAQ or GNA11, CYSLTR2 (encoding G-protein coupled receptor CysLT2R) forms a rare alternative." (PMID 33588787, 2021). "We have previously shown the ability to utilize driver mutations in UM (GNAQ and GNA11 c626A > T and A > C) to detect and monitor circulating tumor DNA (ctDNA) in UM cell lines following drug treatment." (PMID 34789240, 2021). "These genes, encoding phospholipase C β4 and a Gαq-coupled receptor respectively, are typically mutated in GNAQ and GNA11 wild-type tumours, providing an alternative way of activating the Gαq signalling pathway." (PMID 33588787, 2021). "UM tumors often harbor a tumor-initiating mutation in GNAQ or GNA11 with secondary mutation in EIF1AX, SF3B1, SRSF2, or BAP1 that determines metastatic potential." (PMID 34771666, 2021). "In 135 of these patients, an oncogenic GNAQ or GNA11 variant, which allows unequivocal detection of ctDNA in the plasma, was found in the tumor." (PMID 34291585, 2021). "One (2.3%) UM tumor had mutations in both genes and one tumor had two different mutations in GNA11, while seven (16.7%) were GNAQ/11 wild type." (PMID 31173078, 2019). "In an attempt to relate similarities between GNAQ/GNA11 mutation profiles to different tumor entities, we performed unsupervised hierarchical cluster analysis." (PMID 31336681, 2019). "Considering the hallmark driver mutations in the GNAQ and GNA11 paralogs were observed in 100% of cases, a model of tumor evolution based on genetic mutational events progressively occurring in all the four tumor subgroups is provided." (PMID 29156643, 2017). "A concomitant GNA11 mutation was present in this tumor while immunohistochemistry showed intact nuclear BAP1 expression." (PMID 26769193, 2016). "Recurrent mutations in GNAQ and GNA11 initiate UM development while tumour progression is correlated with monosomy of chromosome 3 and gain of chromosome 8q." (PMID 25764247, 2015). "A comparable PFS improvement to that in the overall population was observed in patients with tumours harbouring a mutation in GNAQ or GNA11." (PMID 26059332, 2015). "Sanger sequencing of tumor DNA had previously shown GNAQ/GNA11 mutant alleles in 5 of the 22 patients." (PMID 23634288, 2013). "In the same series, GNA11 mutations were more common in locally advanced tumours and in tumours of the ciliochoroidal region." (PMID 21773036, 2011). "The tumor had mutations in GNA11 (p.Q209P) and BAP1 (p.S583fs)." (PMID 40283643, 2025). "The findings of GNA11/Q single mutations in hyperplastic regions adjacent to double-mutant APAs indicate that GNA11/Q mutations may arise prior to CTNNB1 mutations in the development of these tumours." (PMID 40725432, 2025). "The tumor had mutations in GNA11 (p.Q209L) and BAP1 (c.68-13_82del28)." (PMID 40283643, 2025). "In their study, these authors concluded that GNA11 mutated UMs have worse prognosis, and it is associated with high risk cytogenetic, mutational and molecular tumour characteristics that might be determined, at least in part, by differential DNA-methylation." (PMID 35804836, 2022). "Nevertheless, even in the absence of statistically significant results, several investigations have suggested a more aggressive course of tumours with the mutated GNA11 gene, due to the general observation of a trend towards longer survival among patients with tumours carrying GNAQ mutations." (PMID 35804836, 2022). "It has also been questioned whether the type and location of mutation in the GNAQ and GNA11 genes may affect the progression of these tumours." (PMID 35804836, 2022). "The role of GNA11 as an oncogene and the occurrence of mutations in tumor samples are well studied." (PMID 35620468, 2022). "The GNA11 Q209L mutation was detectable in DNA derived from the primary tumor and in WGA CTCs." (PMID 32913999, 2018). "Exploratory endpoints include efficacy in tumours with GNAQ or GNA11 mutations." (PMID 26059332, 2015).
tumor (continued). "Based on the assumption that every tumor cell within a mutant UM l either carries a GNAQ or GNA11 mutation we were able to calculate the fractional abundance (FA), which represents the ratio between cancer cells and non-cancer cells (e.g. fibroblasts, immune cells) within the tumor." (PMID 26462151, 2015). "Using the Tumor-Node-Metastasis (TNM) system of cancer staging, pathology demonstrated a pT4aN2aM0, stage IIIC, BRAF wild-type, GNA11 mutated tumor with 3 of 13 lymph nodes showing micro-metastases." (PMID 41030443, 2025). "Akin to uveal melanoma, BNM frequently harbors GNAQ and GNA11 mutations which drive a low tumor mutational burden (TMB) and create an immunosuppressive tumor microenvironment (TME) via the reduction of immune cell infiltration." (PMID 41030443, 2025). "By contrast, typical molecular alterations of these tumours include gain-of-function mutations in GNAQ, GNA11, PLCB4 or CYSLTR2 as well as chromosomal alterations including gains on chromosome arms 8q and 6p as well as losses on chromosome arms 1p and 6q." (PMID 40358711, 2025). "Circulating tumor DNA (ctDNA) levels based on GNAQ and GNA11 mutations were available in 8 patients; after 3 months Of tebentafusp treatment, 5 showed reduced Or stable ctDNA levels, and 3 showed an increase (median OS: 24.5 vs. 3.3 months; p = 0.13)." (PMID 40913640, 2025). "Mutations in GNAQ and GNA11 genes cause continuous activation of GPCR signaling, implicated in promoting cell growth, tumor cell invasion, and drug resistance in UM." (PMID 39061150, 2024). "High tumor expression of LHCGR and GNRHR in APAs with CTNNB1 (and GNA11/Q) mutations has been a rationale for the link between the disease onset and pregnancy, menopause, or puberty." (PMID 38505749, 2024). "The mutant allele abundance increased with tumor progression, while an increase in the wild-type allele frequency has been observed in UM tumors with mutations in GNAQ, GNA11 or PLCB4, indicating a complex relationship between these genetic alterations." (PMID 38920653, 2024). "Since the initial UM sequencing studies, there has been controversy about the possible involvement of the GNAQ and GNA11 genes in the prognosis of these tumours." (PMID 35804836, 2022). "Thus, they proposed that the survival data, combined with the predominance of GNA11 mutations in metastasis, raises the possibility that GNA11-mutant tumours may be associated with a higher risk of metastasis and poorer prognosis than those tumours bearing GNAQ-mutants." (PMID 35804836, 2022). "Analysis of tumour biopsies (n = 63) showed that 61 (97%) had likely loss of one copy of BAP1, 23 (37%) had mutations in the gene encoding GNAQ, 26 (41%) in GNA11, three (5%) in CYSLTR2, one (2%) in PLCB4 and 11 (17%) in SF3B1." (PMID 36229663, 2022). "BAP1 mutations are thought to appear after the GNA11 or GNAQ mutations, correlating with a gratly increased risk for tumor progression." (PMID 33903674, 2021). "Results showed that GNA11 was overexpressed in ESCC tissues compared with para-tumor tissues (final score 1.57 vs. final score 0.14, p < 0.05)." (PMID 34568004, 2021). "IHC manifested that the expression of GNA11 can differentiate ESCC tissues with para-tumor tissues (p < 0.05), but it cannot be used to differentiate different pathological grades and clinical stages (p > 0.05)." (PMID 34568004, 2021). "The expression level of GNA11 in tumor tissues and para-tumor tissues was evaluated by staining intensity (color score) and the percentage of positive cells (area score)." (PMID 34568004, 2021). "In examining five key mutations in UM (GNAQ, GNA11, BAP1, SF3B1 and EIF1AX), the xenograft tumours matched the genomic signature of the original patient tumours in 83% of cases." (PMID 34149931, 2021). "IHC analysis further confirmed that GNA11 protein was overall more abundant in ESCC tissues compared with para-tumor tissues." (PMID 34568004, 2021).
tumor (continued). "It is known that posterior UMs carry specific mutations: in 94% of all tumours, a mutation in either the GNAQ or GNA11 gene has been found." (PMID 32998469, 2020). "The limitation of this report is lacking additional genetic analysis such as looking for GNAQ, GNA11, NRAS mutations, or tumor mutation burden." (PMID 33327228, 2020). "GNA11 p.Q209L and GNAQ p.Q209P were the most frequent tumor-specific mutations, with four more in the same genes identified each in one patient." (PMID 33348918, 2020). "GNA11 p.Q209P, GNA11 p.R183C, GNAQ p.Q209L, and GNAQ p.Q209R mutations were identified each in one tumor sample." (PMID 33348918, 2020). "All but one tumour have a known UM driver gene mutation (GNAQ, GNA11, BAP1, PLCB4, CYSLTR2, SF3B1, EIF1AX)." (PMID 32415113, 2020). "Genetic analysis of tumor tissue was performed using a diagnostic biochip (EIMB RAS, Russia) for the detection of most common somatic mutations in the BRAF, NRAS, KIT, GNAQ, GNA11, MAP2K1, and MAP2K2 genes." (PMID 30782194, 2019). "Genetic analysis of the tumor was performed using a diagnostic biochip for the detection of somatic mutations in the BRAF, NRAS, KIT, GNAQ, GNA11, MAP2K1, and MAP2K2 genes, Sanger sequencing for searching germinal mutations in the CDKN2A gene." (PMID 30782194, 2019). "Most UMs harbor one Gq pathway mutation (GNAQ, GNA11, CYSLTR2, or PLCB4), one BSE mutation (BAP1, SF3B1, or EIF1AX), and a few recurrent CNAs, in 100% of tumor cells." (PMID 29317634, 2018). "An initial event, common to all tumor groups, is represented by GNAQ and GNA11 mutations, determining constitutive MAPK activation." (PMID 29156643, 2017). "UM is a rare tumor for which only recently the first step in the molecular etiology was revealed with the identification of GNAQ and GNA11 mutations." (PMID 26368812, 2015). "In light of its ubiquitous expression we also performed the analysis of the GNA11 gene (exon 5) in the same tumor set." (PMID 19718445, 2009). "Thus, this study explored DNA vaccination as a measure to educate the immune system to recognize the most common UM-associated Q209L tumor driver mutation in GNAQ and GNA11 G-alpha proteins." (PMID 41681951, 2026). "In a clinical setting where tumor tissue is unavailable, comprehensive screening for all oncogenic mutations in both paralog genes GNAQ and GNA11 as well as in CYSLTR2 and PLCB4, would be necessary to improve the detection rate of tumor-derived DNA in ocular fluids." (PMID 40461505, 2025). "Conversely, GNA11 mutations were associated with Class 2 tumors (p = 0.0005), PRAME(+) status (p = 0.05), increased patient age (p = 0.002), increased tumor diameter (p = 0.004) and tumor thickness (p = 0.002), and they showed a near-significant association with ciliary body involvement (p = 0.06)." (PMID 41387680, 2025). "Tumor-intrinsic P2RY6 has been shown to activate the GNAQ/GNA11–PLCB pathway." (PMID 41383622, 2025). "Tumor samples that were negative for GNAQ/GNA11 mutations by Sanger sequencing were analyzed by deep amplicon sequencing." (PMID 40461505, 2025). "Targeted next-generation sequencing of isolated tumour DNA revealed wildtype sequences for BRAF, KIT, NRAS and GNA11 while showing a gain-of-function mutation of GNAQ (p.Q209L) with a variable allele frequency (VAF) of 41.4% as well as a variant of SF3B1 (p.R625H) with a VAF of 39%." (PMID 40358711, 2025). "Together these results indicated that GNA11 may serve tumor suppressive roles in the progression of LUADs, and may represent a novel biomarker for this disease." (PMID 37396036, 2023). "UM and CM carry different tumor initiating-mutations, GNAQ, GNA11, CYSLTR2, PLCB4 in UM and BRAF, NRAS, NF1 in CM, and show a different frequency of mutations (mutational burden), very high for CM (>10 mutations per megabase) and very low for UM (0.5 mutations per megabase)." (PMID 37958591, 2023). "As a member of the G protein family, GNA11 plays an important role in tumor progression." (PMID 35879975, 2022).
tumor (continued). "Additionally, they found that patients with GNA11-mutant tumours had poorer disease-specific survival (60.0 vs. 121.4 months p-value = 0.03) and OS (50.6 vs. 121.4 months p-value = 0.03), than those with tumours lacking GNA11 mutations." (PMID 35804836, 2022). "The authors concluded that the univariate analysis of patients with tumours harbouring mutations in GNAQ or GNA11 genes was not significantly lower than in wild-type tumours." (PMID 35804836, 2022). "Besides, our team further explored the performance of anti-GNA11 autoantibody as a biomarker in different subgroups including lymphatic metastasis, differentiation, distance metastasis, family tumor history, TNM stage, gender, and age." (PMID 34568004, 2021). "Both tumours in our study did not have a mutation in any of the hotspots of GNAQ or GNA11, confirming the mutual-exclusivity of these mutations." (PMID 33588787, 2021). "One case (Case 23) harbored two simultaneous mutations of GNA11 Q209L in exon 5 and GNAQ T96S in exon 2, which might indicate the tumor specimen contained a heterozygous population of tumor cells." (PMID 34830903, 2021). "Paired baseline and on-treatment samples (time from baseline to on-treatment sample 0.9–11.3 months) from 17 patients were sequenced and the driver GNAQ, GNA11 and CYSLTR2 mutations identified in the tumor were confirmed by NGS in the baseline and/or on-treatment ctDNA samples in 16/17 patients." (PMID 33917514, 2021). "This mutation was found in 2 tumours (~ 2%), which were both GNAQ and GNA11 wild-type." (PMID 33588787, 2021). "In both patients, canonical mutations in GNA11 and BAP1 were present in all tumor samples." (PMID 34400647, 2021). "Assessment of known UM driver genes revealed an oncogenic driver mutation in 102 of 103 tumours: 51 in GNAQ (48 p.Q209P/L, two p.R183Q, one p.G48L), 46 in GNA11 (44 p.Q209L/P, two p.R183C), five in PLCB4 (three p.D630Y, two p.D630N) and two in CYSLTR2 (p.L129Q)." (PMID 32415113, 2020). "Although the predictive value of mutations in G-protein genes GNA11 and GNAQ in patients with primary CNA melanocytic neoplasms remains unknown, a lot of studies are held to find out if this feature might be useful for tumor diagnostics." (PMID 39518110, 2024). "No tumor presented concomitant variants in GNAQ/GNA11 and in SF3B1 or BAP1." (PMID 34359736, 2021). "However, applying less stringent cutoff levels to the data obtained from the two ctDNA-negative patients who had GNA11 mutations confirmed that no mutant reads were evident in their tumor cells (0% and 0.07%)." (PMID 23634288, 2013). "In vivo experiments further showed that inhibition of INPP5A dramatically reduced tumor burden and metastasis in a mouse model of GNAQ or GNA11-mutant UVM." (PMID 39995872, 2025). "The most frequent genetic mutations are in guanine nucleotide-binding protein alpha 11 (GNA11) and guanine nucleotide-binding protein q polypeptide (GNAQ), which are somatic in tumor cells." (PMID 40283643, 2025). "The performance of anti-GNA11 autoantibody in clinical variables (including lymphatic metastasis, differentiation, distance metastasis, TNM stage, family tumor history, gender, and age) was further explored." (PMID 34568004, 2021). "Immunohistochemistry (IHC) was used to evaluate GNA11 expression in ESCC tissues and para-tumor tissues." (PMID 34568004, 2021). "Tumor DNA from a cohort of 100 UM patients from Moorfields Biobank (UK) that had undergone enucleation were sequenced for known UM driver genes (BAP1, SF3B1, EIF1AX, GNAQ, and GNA11)." (PMID 36077643, 2022). "The expression of GNA11 between ESCC tissues and para-tumor tissues evaluated by IHC." (PMID 34568004, 2021).